CCND1 (cyclin D1)
Diseases named in the same sentence as CCND1 in open-access papers (continued):
Sharing a sentence is not in itself a finding about the gene and the disease.
thyroid cancer (54 papers, 2002 to 2025). "One of the mechanisms linked with protein overexpression is the amplification of Cyclin D1 that was first documented in thyroid cancer." (PMID 32198408, 2020). "Cyclin D1 protein is aberrantly overexpressed in thyroid cancers, but mutations of the CCND1 gene are rare in these tumors." (PMID 30428594, 2018). "The association of CCND1 rs9344 (G870A) polymorphism and risk of thyroid cancer has been reported in a few studies." (PMID 30428594, 2018). "Cyclin D1 protein is overexpressed in human thyroid cancers that have causal links to environmental radiation exposures at nuclear test sites." (PMID 16203246, 2005). "Our study suggests that in thyroid cancer, hypomethylation of the CCND1 promoter may be the cause of CCND1 overexpression seen in other studies." (PMID 36975440, 2023). "Previous studies have identified associations between Cyclin D1 expression levels and tumor differentiation, aggressive biological behaviors as well as metastatic disease in thyroid cancer, highlighting the potential role of Cyclin D1 as a prognostic parameter." (PMID 32198408, 2020). "However, mutations and amplification of the CCND1 gene have rarely been found in the differentiated thyroid cancer." (PMID 30428594, 2018). "Constitutive overexpression of cyclin D1, caused by chromosomal abnormalities, gene amplification or other post-translational mechanisms has been reported in different types of tumours including thyroid cancer." (PMID 15292926, 2004). "Immunohistochemistry revealed tumor marker patterns characteristic of malignancy, including parafibromin and E-cadherin loss and positivity for markers such as galectin-3 and cyclin D1 in parathyroid cancers and TTF1 and CK19 in thyroid cancer." (PMID 40142758, 2025). "In thyroid cancer, its migratory function is executed through similar ceRNA interactions, targeting miR-338-3p/CCND1 and miR-423-5p/SOX12." (PMID 40828427, 2025). "This interaction regulated the expression of proteins such as SOS1, c-myc, and CCND1, consequently inhibiting abnormal proliferation of thyroid cancer cells." (PMID 37470034, 2023). "More studies are focusing on NR2F1-AS1, which promotes the proliferation and migration in thyroid cancer by regulating the miRNA-338/CCND1 axis." (PMID 34408977, 2021). "miRNA‐338‐3p inhibited cell growth and metastasis while reduced apoptosis of thyroid carcinoma cells by mediating CCND1." (PMID 34130587, 2021). "CD44-ICD enriched CREB recruitment to the cyclin D1 promoter, thus promoting cyclin D1 activity, a regulator of protein transcription and cell proliferation, in thyroid carcinoma cells." (PMID 34944493, 2021). "ARV-825 induced BRD4 protein degradation and downregulation of its targets, including c-Myc, Bcl-xL and cyclin D1 in thyroid carcinoma cells." (PMID 32163373, 2020). "In TPC-1 cells and primary human thyroid carcinoma cells ARV-825 induced BRD4 protein degradation, causing downregulation of BRD4-dependent oncogenic proteins, including c-Myc, Bcl-xL and cyclin D1." (PMID 32163373, 2020). "Further studies are necessary to elucidate the cytoplasmic cyclin D1-dependent mechanisms that control cell adhesion and migration in thyroid cancer." (PMID 30428594, 2018). "This was supported by our findings that ectopic expression of PAX3 markedly up- regulated FOXO3a downstream target genes, such as p21, p27, p130, Bim and TRAIL, and down-regulated another target gene cyclin D1 in thyroid cancer cells." (PMID 27458157, 2016). "Our studies identified Cyclin D1 as a therapeutic target for thyroid tumors, and provide a rationale for preclinical and clinical studies aimed to assess the efficacy of inhibitors of Cyclin D1 function in thyroid cancer." (PMID 26431489, 2015). "We next performed some experiments to further corroborate the dependency of thyroid cancer cells upon Cyclin D1, MASTL and COPZ1 activity." (PMID 26431489, 2015).
thyroid cancer (continued). "In contrast, downregulating FOXP3 expression in thyroid cancer resulted in the downregulation of NF-κB subunit p65 and cyclin D1 concomitantly with the upregulation of caspase-3 levels." (PMID 26305693, 2015). "In thyroid carcinoma overexpression of Cyclin D1 at mRNA and protein level has been documented, and has been suggested to contribute to tumor progression." (PMID 26431489, 2015). "It is reported that Let-7 miRNA inhibited cell growth partially by decreasing mRNA expression of cell cycle stimulators MYC and cyclin D1 in thyroid cancer." (PMID 23806108, 2013). "In our earlier study, we demonstrated that cyclin D1 gene expression levels were higher in malignant thyroid tumours (PTC, MTC), when compared to those in NG or FA groups." (PMID 21219594, 2011). "Previous studies in cancer models, including thyroid cancer, have cited a role for NF-κB in malignant cell proliferation by transcriptional regulation of cyclin D1, CDK2, cyclin E and c-Myc." (PMID 20492683, 2010). "This is in accordance with our results showing that, in thyroid cancer cell lines a decrease in proliferation parallel with a decrease in cyclin D1 levels." (PMID 19878585, 2009). "Cyclin D1 isknown to be overexpressed in human thyroid carcinomas and in vitro addition of aPPARγ agonist to human ATC cell linessuppresses cyclin D1 levels, confirming thatthis effect is related to alterations in PPARγ rather than TRβ." (PMID 18989374, 2008). "Knockdown of ZFAS1 led to decreased proliferation, migration, invasion, and EMT in thyroid carcinoma cells, in part by increasing levels of anti-tumor microRNAs such as miR-302a-3p, and subsequently reducing cyclin D1 (CCND1) expression, which promotes cell cycle progression." (PMID 41154428, 2025). "Different reports described the overexpression of cyclin D1 in thyroid cancer." (PMID 34405392, 2022). "It is suggested that TREM2 exerts a pro-proliferative effect on thyroid cancer cells by activating the NF-κB signaling pathway to upregulate the expression of cyclin D1 and Bcl2, indicating that TREM2 may be located upstream of the NF-κB signaling pathway." (PMID 36438899, 2022). "Furthermore, CD44 ICD drives the proliferation of thyroid cancer by increasing cyclin D1 expression and the activity of CREB." (PMID 33804427, 2021). "In terms of gene products most frequently targeted by the differentially expressed miRNAs, the top 30 most affected validated genes included MDM2, CDK6, DICER1, CCND1 (encoding cyclin D1), and CDKN1A (encoding p21), all exhibiting some association to the development or progression of thyroid cancer." (PMID 34676499, 2021). "Various studies showed that BTG1 overexpression suppressed proliferation, migration and invasion, and induced apoptosis and cell cycle arrest of lung, kidney, breast, esophageal, hepatocellular, nasopharyngeal, and thyroid cancers with Cyclin D1, Bcl-2, and MMP-9 hypoexpression." (PMID 33330092, 2020). "Next, the expression levels of CTNNB1, ACTB, and CCND1 in thyroid carcinoma were also determined." (PMID 33363164, 2020). "Using a nuclear cyclin D1 immunostaining proportion of the cut-off threshold for malignant thyroid neoplasm positivity from thyroid neoplasm was set at 46%, we found that cyclin D1 positivity in FNA samples was significantly associated with histologic type (P < 0.0001)." (PMID 30885146, 2019). "Thus, the level of cyclin D1 overexpression may be important parameters in estimating tumor growth and metastatic potential of thyroid malignant tumors towards clinical features." (PMID 30885146, 2019). "Moreover, it has been suggested that Pin1 may promote cyclin D1 overexpression directly or through accumulation of beta-catenin in thyroid cancer cells." (PMID 21219594, 2011). "Conditional media from CAFs overexpressing PROS1 significantly upregulated the expression of β‐catenin, C‐myc, CCND1, and p‐SMAD2 in thyroid cancer cells." (PMID 40433916, 2025).
thyroid cancer (continued). "In thyroid cancer, NR2F1-AS1 promotes proliferation and inhibits apoptosis via the miR-338-3p/CCND1 and miR-423-5p/SOX12 pathways." (PMID 40828427, 2025). "In thyroid cancer tissues with high KAT8 expression, KAT8 knockdown decreased the levels of cyclin D1 (CCND1) and D3 (CCND3), critical regulators of the G1/S transition, resulting in G1-phase cell cycle arrest and suppressed thyroid cancer cell proliferation." (PMID 40508066, 2025). "They indicated that the suppression of PVT1 causes cell cycle arrest at G0/G1 phase and significantly decreases cyclin D1 expression, thyroid stimulating hormone receptor (TSHR) expression, and the proliferation of thyroid cancer cells in ATC cell line." (PMID 32760219, 2020). "In thyroid cancer cells, oncogene activation prevented TGF-ß/SMAD-dependent p27 repression and CDK2/SMAD3 phosphorylation, leading to p65 up-regulation, which repressed BAX, induced cyclin D1 and promoted TGF-ß-dependent growth." (PMID 37954148, 2023). "Furthermore, canagliflozin inhibited G1/S phase transition and cyclin D1, cyclin D3, cyclin E1, cyclin E2, and E2F1 expression levels in thyroid cancer cell." (PMID 35148777, 2022). "Moreover, knockdown of CNTN1 significantly repressed the expression of cyclin D1 (CCND1), a target gene of the Notch1 pathway, indicating CNTN1 to potentially regulate the expression of CCND1 by activating Notch1 in thyroid cancer." (PMID 33194679, 2020). "Only three miRNA–gene pairs (miR-876-3p-CTNNB1, miR-876-3p-ACTB, and miR-876-3p-CCND1) revealed a statistically negative expression relationship in thyroid carcinoma." (PMID 33363164, 2020). "Thus we envisage that Cyclin D1, MASTL and COPZ1 are attractive targets for new therapeutic approaches for thyroid cancer which spare normal cells and which would thus have limited side effects." (PMID 26431489, 2015). "Collectively, our study identified Cyclin D1, MASTL and COPZ1 as thyroid cancer cell specific vulnerabilities, suggesting that they could provide a common therapeutic target in thyroid cancer treatment." (PMID 26431489, 2015). "Although the copy number of cyclin D1 gene is amplified in a number of human neoplasms, neither major genetic alterations nor amplification of this gene has been found in thyroid cancers, but mainly a strong nuclear cyclin D1 localization." (PMID 23591524, 2013). "In thyroid cancer cells, the intracellular protein fragment CD44-ICD released by CD44 proteolytic cleavage translocates to the nucleus, and enhances the binding of transcription factor CREB with the cyclin D1 promoter to promote cyclin D1 transcription and cell proliferation." (PMID 36042265, 2022). "Besides, CCND1 and CTNNB1 were also reported to function as oncogenes in thyroid cancer." (PMID 33363164, 2020). "The cyclin D1 staining of stromal cells (not seen in WT and RET/PTC3 thyroids) is puzzling and not reported in human thyroid carcinomas." (PMID 18985036, 2008). "Our results also show that p27Kip1 and cyclin D1 proteins are important in the regulation of proliferation via BRAFV600E-ERK signalling and BRAF does not seem to be a major protein for the survival of thyroid cancer cells." (PMID 19878585, 2009).
head and neck cancer (53 papers, 2006 to 2025). A primary or metastatic malignant neoplasm affecting the head and neck. "CCND1 (Cyclin D1) gene amplification, a relatively frequent event in head and neck cancer, has been associated with HPV-negative status and poor survival." (PMID 39328208, 2024). "In head and neck cancer, amplification of CCND1 is linked to the appearance of heterogeneous proliferative lesions to cancer in situ, as well as a poor clinical outcome." (PMID 37481637, 2023). "Amplification of the cyclin D1 gene was shown to be occurring in early stage of head and neck cancer and significantly associated with high proliferative activity." (PMID 21537090, 2011). "On the other hand, cyclin D1 (encoded by CCND1, which frequently shows gene amplification in head and neck cancers) is a key downstream effector of EGFR signaling and associated pathways, promoting cell cycle progression and contributing to the hyperproliferative phenotype of OL." (PMID 40805130, 2025). "The CCND1 amplified subtype of head and neck cancer (c3) was also associated with poor survival." (PMID 33272320, 2020). "Other authors have reported that cyclin D1 gene polymorphism (CCND1) was associated with the early onset of head and neck cancer, and contributed to susceptibility to head and neck cancer, particularly in young non-smokers and non-drinkers in a case-control study." (PMID 24086646, 2013). "Overexpression of cyclin D1, associated with the amplification of the CCND1 gene, has been reported in oesophageal, lung, breast and head and neck carcinomas." (PMID 25907675, 2015). "Analysis of the relationships with cell cycle regulators specially relevant in head and neck cancers, such as Cyclin D1 or growth factors, would be of interest." (PMID 16598186, 2006). "While the level of expression of cyclin D1 in recurrent NPC was similar to that of previously untreated head and neck cancer, the level of p16 expression in recurrent NPC samples was much lower than that reported for previously untreated cancer." (PMID 16953893, 2006). "In addition, p16—a CDKI closely related to the HPV 16 status frequently seen in head and neck cancers—is typically downregulated in tumors with high cyclin D1, and its presence tends to indicate better treatment response and survival." (PMID 40429363, 2025). "Cyclin D1 is an important cell cycle regulator, being one of the cyclin-dependent kinases, and is controlled from chromosomal region 11q13, which is known to undergo amplification in several cancers, including head and neck cancer." (PMID 24206575, 2013). "An increased level of cyclin D1 expression has been reported in a number of malignancies including esophageal, ovarian, breast, uterine, colon, lung, prostate, lymphoma, as well as head and neck cancers." (PMID 16953893, 2006). "However, according to previous studies, the role of Cyclin D1 as a prognostic marker remains controversial and there is no consensus on the use of Bcl-2 as a prognostic marker for squamous cell carcinomas among head and neck cancer patients either." (PMID 23451060, 2013). "We conclude that CCND1, AXL, CDKN2A, TERT, and EZH2 are the hub genes involved in cisplatin resistance in head and neck cancer that have significant mRNA expression and effect on overall survival." (PMID 36715825, 2023). "The cell cycle regulatory gene CCND1 located in 11q13.3 is a downstream effector of EGFR and is commonly deregulated in various cancers including head and neck cancer." (PMID 31159251, 2019).
head and neck cancer (continued). "Reportedly, miR-503 suppressed the endogenous CCND1 both at protein and mRNA levels by binding to the 3′ UTR of the CCND1 gene and inhibited cell growth by reducing S-phase cell populations in human head and neck carcinomas." (PMID 23967867, 2013). "The patient with the FANCL (head and neck cancer) received olaparib and experienced a TTF for 12 months until progress, whereas the FA patient with CDK4/CCND1 amplification deceased after 13 months, with the first treatment being olaparib (6 months) and then palbociclib (7 months)." (PMID 38136436, 2023). "Inhibition of STAT5b, but not of STAT5a, in xenograft models of head and neck carcinomas via antisense oligonucleotides repressed tumor growth and hindered expression of the STAT5-regulated genes cyclin D1 and Bcl-XL." (PMID 17997837, 2007).